CD9 (CD9 molecule)
Diseases named in the same sentence as CD9 in open-access papers (continued):
Sharing a sentence is not in itself a finding about the gene and the disease.
cancer (continued). "In conclusion, fully validated antibodies and well-designed functional studies may help to elucidate further the role of CD9 in cancer progression and patient clinical outcome." (PMID 37007105, 2023). "Fibrocytes that were identified in lung tumors as CD45+CD44+CD162+CD11b+F4/80+CCR2/5+CD9+ cells had lost the monocyte marker Ly6C compared to bone marrow fibrocytes, indicating a maturation process in the cancer microenvironment, reminiscent of monocyte to macrophage differentiation in tumors." (PMID 36241617, 2022). "Tetraspanins, like CD9, often combine with different molecules they assemble into extracellular vesicles (EVs) called exosomes, whose levels resulted as increased in cancer patients." (PMID 35563166, 2022). "Thus, MSC treatment with dextran-coated IONPs and ionomycin helped envisage a pharmaceutical strategy involving CD9 to prevent cancer metastasis." (PMID 35103937, 2022). "Therefore, the role of CD9 is highly debated and controversial, since its expression in cancer cells has been reported to exert both pro- and anti-migratory functions, probably due to its modulatory activity toward integrins and other transmembrane proteins." (PMID 35563166, 2022). "Interestingly, CD9 has been successfully engineered to load cytosolic proteins or enzymes into EVs, while CD81 has also been mutated to gain the cancer-targeting ability for potential anticancer therapy." (PMID 36559058, 2022). "CD9 has also been shown to be expressed by cancer cells and MSC from different tissues." (PMID 36012583, 2022). "For example, it is known that miR-518f-5p decreases CD9 levels in some types of cancer cells." (PMID 35271606, 2022). "Additionally, high levels of CD9 and CD82 have been associated with a favorable prognosis in different types of cancers, like breast, pancreas, prostate, and lung cancer." (PMID 34830819, 2021). "Therefore, the current meta-analysis was conducted to comprehensively elucidate the prognostic and clinicopathological significance of CD9 expression in cancer patients." (PMID 34493282, 2021). "However, while there is much more information needed in order to establish the prognostic significance of CD9 in cancer, most studies agree on the fact that its expression is related to patients’ survival rates, disease-free interval, or recurrence rates." (PMID 34830819, 2021). "Similarly, CD9-targeting antibodies have been investigated as anti-cancer agents in different types of tumors and CD9 has been proposed as a therapeutic target in gastrointestinal cancer." (PMID 34576100, 2021). "Indeed, previous studies have reported that decreased CD9 expression is generally related to more venous invasion and metastasis as well as poor prognosis in most common type of cancer." (PMID 34493282, 2021). "CD9 is a tetraspanin involved in cell adhesion, metastasis and inflammation in cancer." (PMID 34336652, 2021). "CD9 is ubiquitously expressed in various normal and cancer tissues, and consequently, its expression as a molecular marker is often ambiguous and cancer-dependent." (PMID 34065085, 2021). "CD9 has also been used in human cancer processes, such as metastasis or angiogenesis." (PMID 34493282, 2021). "This suggests that CD9 expression is a valuable survival factor in cancer patients." (PMID 34493282, 2021). "Calibration curves were generated with two most effective combinations (anti‐CD9/Banti‐CD81 and anti‐CD63/Banti‐CD9), resulting in 103 and 104 times higher sensitivity than the EV concentration in human blood plasma from healthy or cancer patients, respectively." (PMID 33664936, 2021). "Therefore, the current meta-analysis was conducted to determine the prognostic and clinicopathological significance of CD9 expression in cancer patients." (PMID 34493282, 2021).
cancer (continued). "CD9 is involved in cell adhesion, motility, sperm–egg fusion, tumorigenesis and metastasis and an inverse correlation between expression of CD9 and metastatic potential and patient survival rate has been established in many types of cancer, including CRC." (PMID 34576100, 2021). "Thus far, DNA hypermethylation in cancer cells has been documented for at least 6 members of the tetraspanin family, including CD9, CD81, CD82, CD151, TSPAN1, TSPAN3, and Uroplakin." (PMID 33919420, 2021). "CD9/CA IX is co-localised within low pH cultured cancer cells." (PMID 31790614, 2020). "In general, PCa-associated exosomes procured from clinical samples reveal cargo that contains cancer-related proteins such as CD9, CD81, and TSG101, Annexin A2, Fatty Acid Synthase (FASN), and prostate-specific membrane antigen (PSMA: a PCa-specific biomarker)." (PMID 32121073, 2020). "CD9 protein expression is typically decreased in aggressive and advanced stage cancers." (PMID 32224917, 2020). "The role of CD9 in cancer remains controversial and seems to vary among different cancer types." (PMID 32411706, 2020). "As noted by the authors, the specificity and generalizability of the nPES platform could be improved further by replacing the secondary anti-CD9-AuNR probe with additional cancer-specific probes." (PMID 31134179, 2019). "However, these CD9 or CD63 antibodies cannot selectively bind cancer-derived EVs; thus, further investigations to find cancer-specific antigens on the surface of EVs are needed." (PMID 31447954, 2019). "In this approach, EVs are captured with a cancer-selective antibody, hybridized with gold nanorods conjugated with an antibody to the EV surface protein CD9, and quantified by their ability to scatter light when analyzed using a fully automated dark-field microscope system." (PMID 31921310, 2019). "Meanwhile the case of many types of cancer cells, where CD9 promotes cell proliferation and migration, may share similarities with the mechanisms, whereby CD9 drives renal disease via aberrant expression in PECs." (PMID 31341160, 2019). "Interestingly, many proteins from these pathways are also CD9 or other tetraspanin protein partners and are all involved in cancer progression." (PMID 29416746, 2018). "Indeed, CD9 is often downregulated in advanced stages of cancer, and its absence is a sign of poor prognosis in patients with lung, breast, colon, skin, ovary, uterus, stomach, oral cavity, thyroid, prostate, and hematopoietic malignancies." (PMID 30356731, 2018). "However, differences between the groups were significant when PSMA was normalized by CD9, which is an EV-specific marker (cancer, 46.21, BPH, 10.93, p < 0.05)." (PMID 29584777, 2018). "In the field of cancer, targeting CD9 is widely studied as a potential clinical tool." (PMID 30356731, 2018). "Second, the number of CD9-GFP-loaded N-ALE per cell almost doubled for cancer cells (from 0.26 ± 0.05 to 0.48 ± 0.06 [106 cells] and 0.39 ± 0.07 to 0.59 ± 0.07 [113 cells] for FEMX-I and MDA cells, respectively), but not for MSCs (0.275 ± 0.06 to 0.34 ± 0.07 [62 cells])." (PMID 28129640, 2017). "The role of CD9 in cancer development remains a matter of controversy." (PMID 29383115, 2017). "CD9 protein was found to be a potential cancer stem cell marker in different types of cancer." (PMID 26573230, 2016). "CD9 is known to block or facilitate cancer cell motility and metastasis dependent upon entity." (PMID 27572323, 2016). "Based on its physiological importance and its putative involvement in cancer metastasis, we sought to investigate whether CD9 has a role in the cellular interaction between human BCCs and bone marrow-derived multipotent mesenchymal stromal cells (MSCs)." (PMID 25762645, 2015). "Beyond the cell cycle regulator CDKN1B (12p13.1), further potentially relevant cancer genes on 12p may for example include CD9, ING4, and BCL-G." (PMID 26293672, 2015).
cancer (continued). "However, an expanding body of literature has shown the contradictory outcome that tetraspanin CD9 is also vital in promoting cancer progression in several types of cancer." (PMID 24520284, 2014). "In pathological conditions, such as cancer, the expression levels of CD9 may induce marked effects on cell motility through a change in the membrane compartmentalization of CD9P-1, thus favoring metastasis." (PMID 24520284, 2014). "Together, these key findings support a model in which tetraspanin CD9 may have considerable therapeutic potential for the treatment of metastasizing cancers." (PMID 23840773, 2013). "Finally, CD9 plays a role in many cellular processes including differentiation, adhesion, signal transduction, growth, and in the suppression of cancer cell motility and metastasis." (PMID 23555683, 2013). "Strong CD9 expression in metastasizing cancers indicates that this protein may be a novel target for regulating the invasive phenotype of these cells." (PMID 23840773, 2013). "An emerging consensus is that α6β4 complex synergizes with specific molecules such as ErbB2, EGFR, Ron, Fyn, c-Met, protein kinase C, CD151, and CD9 to activate key signaling pathways for the invasion and migration of carcinoma cells via activation of signaling molecules such as PI3K." (PMID 24015244, 2013). "Next, we examined whether the selected scFv-Fcs could recognize endogenous CD9 expression on human cancer cells using flow cytometry and immunofluorescence confocal microscopy." (PMID 22989299, 2012). "In pathological conditions such as cancer, variation in the expression level of CD9 or CD81 may induce dramatic effects on cell motility through a change in the membrane compartmentalization of CD9P-1, thus favoring metastasis." (PMID 20574531, 2010). "Although CD9 has been implicated in cell fusion, migration and cancer progression, the detailed function of this protein is not completely understood and likely depends on interactions with different protein partners, which are not yet all known." (PMID 17848953, 2007). "Hence, targeting CD9 with monoclonal antibodies may offer insights into a new therapeutic approach to improve the prognosis of cancer patients undergoing chemotherapy." (PMID 38389703, 2024). "The precise mechanisms by which CD9 mediates this communication are still being investigated, but the involvement of CD9 in exosome packaging and uptake suggests that it may be a promising target for the development of novel cancer therapies." (PMID 37475778, 2023). "Intrigued by the observation that a cathepsin B-dependent cleavage activity on CD9-RFP recombinant protein is evident in a cathepsin B-overexpressing cancer cell line, we wondered whether the same phenotype could also be reproduced in a non-cancer cell line like HEK293 cells." (PMID 36579638, 2023). "Notably, the higher level of CD147/CD9 in serum exosomes could also be detected at an early stage of cancer, with the area under the curve (AUC) of 0.820 among healthy donors versus patients." (PMID 35757760, 2022). "In addition, CD9 is ubiquitously expressed and its anti-cancer functions may be dependent on its expression and interactions with other proteins in exosomes, other cell types such as stroma, and other organ sites." (PMID 32224917, 2020). "In addition, invasion and metastasis may be elevated through preventing lysosomal degradation of MT1-MMP by CD9 in cancer cells." (PMID 24520284, 2014). "Their specificity could be confirmed by recognition of endogenous CD9 expression on cancer cells." (PMID 22989299, 2012). "In contrast, in pancreatic cancer, CD9 plays a role by interacting with α-secretases, such as ADAM9, ADAM10, and ADAM17, to influence the Notch signaling pathway, which in turn promotes cancer development." (PMID 40860827, 2025). "The use of ELISA-based methods for the quantification of proteins specific to cancer-derived exosomes, such as CD44, CD44v6, CD9, EpCAM, and CD81, has been well-documented." (PMID 41573685, 2025).
cancer (continued). "More importantly, several cell adhesion proteins, such as BSG, ITGA2, CD9, SLC3A2 or CD151, were significantly enriched in TuNEPs and shared across cancer types." (PMID 40751052, 2025). "Most of them measured either cancer-related proteins (i.e., PSMA, PCA3, TMPRSS2:EGR, or PSA) or exosomal cell surface proteins (CD9, CD3, EpCAM, or CD81)." (PMID 39859516, 2025). "It should be noted that the same proteins (CD9, CD24, CD63, CD81, MMP9) were common to exosomes of cancer cells and primary cells." (PMID 40310419, 2025). "Some proteins differentially expressed in J774A.1 cells, such as CD9 down-regulation and PYCR up-regulation, are also observed here, indicating cancer-driven metabolic reprogramming." (PMID 39510801, 2025). "The protein CD9 is involved in controlling exosome communication and the epithelial-to-mesenchymal transition (EMT), processes that contribute to cancer progression." (PMID 40491606, 2025). "Previous research has demonstrated that TSPAN proteins, like CD9, CD81, CD151, and TM4SF1, promote cancer metastasis by interacting with integrin α3β1 or α6, which aligns with our functional enrichment results." (PMID 41347075, 2025). "Our investigation revealed that the exosome‐dominated EV subpopulation (Exo), captured using a combination of CD63/CD9/CD81 antibodies, proved effective as an mRNA‐based cancer marker." (PMID 38204202, 2024). "An intriguing observation was that CD9 status affected B-ALL outcome while sparing T-ALL, indicating its context-dependent implications for cancer progression." (PMID 38001171, 2024). "Lastly, these results suggest that EVs from cancer cells and stem cells display cell type-specific expression of CD63, CD9, and CD81." (PMID 38786083, 2024). "Therapeutic monoclonal antibodies (mAbs) targeting different tetraspanin members including TSPAN8, CD9, CD37 and CD151 have been explored in preclinical models and clinical trials for the treatment of hematological malignancies and carcinomas." (PMID 38275818, 2024). "CD81, CD9, TSPAN31, and TSPAN13 are also reported to facilitate cancer cell invasion and metastasis." (PMID 36941633, 2023). "On the other hand, exosomal proteins, such as CD63, CD9, TSG101, and EpCAM, reflecting significant information about the cancer microenvironment, are highly enriched in exosomes derived from cancer cells." (PMID 38005527, 2023). "For example, researchers have shown that blocking CD9 can reduce the uptake of cancer cell fibroblast (CAF)-derived EVs by pancreatic cancer cells, cancer cell migration, and epithelial-to-mesenchymal transition (EMT)." (PMID 39697985, 2023). "Studies have shown that CD9-positive exosomes generated from CAFs can be taken up by SGC cells, which promote cancer cell migration and invasion by activating the MMP2 signaling pathway." (PMID 36717783, 2023). "WB showed that the protein expression of exosome markers, Alix, CD9, and CD63, was increased in NC and ferroptosis-induced MDA-MB-231 cell and 4T1 cell-derived exosomes compared with corresponding cancer cells." (PMID 36949762, 2023). "Mechanistically, CD9 promoted the plasma membrane localisation of the glutamine transporter ASCT2, enhancing glutamine uptake in cancer cells." (PMID 37007105, 2023). "Low affinity anti-CD9 antibody, C9BB, which binds preferentially to CD9 homodimer was used in experiments documenting a shift to heterodimers in cancer cells." (PMID 37007105, 2023). "Pie charts represent the expression profiles of CD9, CD81 and CD63 in percentage of circulating EV particles from representative cancer patients and LC control." (PMID 36582804, 2022). "Among these 16 proteins, proteins reflecting the cellular origin (HLA-DR, HLA-DP, HLA-DQ, CD31, CD41b, CD42a), activation markers (CD62p), EV markers (CD9, CD63, CD81), and cancer related markers (CD44 CD29, CD105, CD146) were found." (PMID 35012489, 2022).
cancer (continued). "However, more importantly, as CD63 and CD9 are also expressed on the surface of EVs released from different cell types, the study of their plasmatic levels could allow obtaining information on the organism's response to the presence of cancer." (PMID 34935096, 2022). "A number of EV membrane proteins, including CD147/basigin and EpCAM, have been selected to pair with the EV markers CD9 or CD63 as biomarker panels for CRC and have been successfully tested for effective cancer detection using blood specimens." (PMID 36612172, 2022). "shRNA silencing of mortalin reduced cancer cell stemness by downregulating ABCG2, OCT-4, CD133, ALDH1, CD9, MRP1, and connexin expression levels, leading to a higher ability to form spheroids." (PMID 35859897, 2022). "Overall, we demonstrated that the surface markers CD9, CD63, and CD81 are sufficient to distinguish between sEV populations derived from different cancer cells." (PMID 35955677, 2022). "Eleven of those proteins were detected in all patients, including the common EV markers CD9, CD63 and CD81, cancer-related markers CD24, CD29, CD44 and CD146, platelet markers CD41b, CD42a and CD62p as well as HLA-DR/DP/DQ." (PMID 35012489, 2022). "Despite the large diversity among tetraspanins, some have been clearly demonstrated to play key roles in cancer, among which CD151 and CD9 represent the most important ones." (PMID 34830819, 2021). "CD9 (Tspan29), CD63 (Tspan30) and CD82 (Tspan27) inhibit metastasis of various cancers, whereas Tspan8 and CD151 (Tspan24) promote metastasis." (PMID 33955149, 2021). "EVs were isolated from 80 serum samples from healthy individuals and cancer patients via polyethylene glycol (PEG)-based precipitation and immunoaffinity separation using antibodies against CD9, CD63, CD81, and EpCAM." (PMID 33808296, 2021). "Cancer patients are characterized by NK cells with altered surface markers, such as CD56 brightness, CD9, CD49a (pro-angiogenic) and PD-1, and TIM-3 (exhaustion), that favor immune escape." (PMID 34638439, 2021). "WB analysis showed enrichment of exosome-related proteins, CD9 and CD63, in the EVs isolated from both cancer and control samples when compared with EV-depleted supernatant." (PMID 31963351, 2020). "The results of our experiments and other studies proved the cancer metastasis suppressor role of CD82 and CD9, clinically connected to the progression, invasion, and metastasis of various malignancies." (PMID 32091301, 2020). "Cancer cells generate copious levels of exosomes; the Munc13-4 is a Ca2+-dependent regulator of Rab-dependent signaling, which confers increased CD63+, CD9+, and ALIX+ exosomal release in cancer cells, which enhances their survival." (PMID 32957534, 2020). "For the purposes of cytometry assays and sorting, we defined CCD133−/CD24+/CD9−as neuronal cancer cells, CD9+/CD44+/CD133− as astro-mesenchymal cancer cells, and CD9+/CD133+ as progenitor cancer cells." (PMID 32641768, 2020). "A multiplexed SPR assay approach with two typical exosomal (CD9 and CD63) and four cancer-specific (CD24, CD44, EpCAM, and HER2) biomarkers was demonstrated, with a prerequisite of sample volume in the range of 5–20 μL." (PMID 31134179, 2019). "We quantified by an ELISA-based technique specific proteins of cancer-derived exosomes (CD44,CD44v6,EpCAM,CD9,CD81,Tspan8,Integrin α6,Integrin β4,CD24,CXCR4)." (PMID 31048929, 2019). "Among the human tetraspanins, Tspan8 and 12, CD9, CD37, CD63, CD81, CD82, and CD151 play a role in cancer progression." (PMID 29946318, 2018). "Proteomic profiling of extracellular vesicles of 60 cancer cell lines (NCI-60) revealed CD81 expression in all 60, while CD9 and CD63 were expressed in about 40 of these cell lines." (PMID 29946318, 2018). "Several cancer cell stemness markers, such as ABCG2, OCT-4, CD133, ALDH1, CD9, MRP1 and connexin were upregulated in mortalin-overexpressing cells that showed higher ability to form spheroids." (PMID 28165047, 2017).